MMP9 (matrix metallopeptidase 9)
Diseases named in the same sentence as MMP9 in open-access papers (continued):
Sharing a sentence is not in itself a finding about the gene and the disease.
tumor (continued). "TAN promotes blood vessel growth and promotes tumor invasion and metastasis through various proangiogenic factors, such as VEGFA, and matrix metalloproteinase-9 (MMP-9)." (PMID 39132507, 2024). "As nanovectors accumulate at tumor sites via the EPR effect, overexpressed MMP-9 can detach the PEG corona to expose RGD and facilitate cellular internalization." (PMID 38474590, 2024). "Within primary tumor, CD163+ was positively correlated with CD163+MMP9+ (r = 0.751, P = 0.0013) and CD68+CD163+CD206+ (ρ = 0.762, P = 9.7E−4)." (PMID 39373616, 2024). "Elevated MMP9 expression facilitates ECM remodeling in fibroblasts and epithelial cells, potentially enhancing tumor invasion and metastasis." (PMID 39234567, 2024). "Studies indicate that astrocytes play a critical role in modulating the protein and matrix composition of tumor cells by releasing MMP-2 and MMP-9, thereby promoting the invasion and metastasis of tumor cells in the brain." (PMID 38577333, 2024). "It is known that MMP is involved in tumor metastasis, and TRAF6 induces MMP-9 expression by binding to BSG." (PMID 38921571, 2024). "MMP-2 and MMP-9 destroy type IV collagen, which is part of the basement membrane, STM, and ensure the invasion of tumor cells into surrounding tissues." (PMID 39274874, 2024). "Subsequently, we performed IHC staining analysis of VM-related markers, including VM markers VE-cadherin, Fibronectin 1 (FN1), SERPINE2, tumor microenvironment markers MMP2 and MMP9, epithelial cell marker E-cadherin and mesenchymal cell marker vimentin." (PMID 38164156, 2024). "In HCT 116 and SW480 cells transfected with miR-497 mimics, the levels of the tumor invasion markers MMP-2 and MMP-9 proteins were significantly reduced compared to control cells via targeting Fra-1, demonstrating that miR-497 inhibits invasion in these cells." (PMID 39858430, 2024). "Main mast cells mediators have been described in the tumor microenvironment, including chymase, tryptase, VEGF, Histamine, TNF-α, MMP2, MMP-9, TIMPs, NGF, and sphingosine-1-phosphate." (PMID 38969910, 2024). "The transcription levels in tumor tissues of related proangiogenic cytokines or chemokines such as SDF-1, MMP-2, MMP-9, and VEGFR2 treated with CPA or 5-Fu were also determined using RT-PCR." (PMID 39119610, 2024). "MMP‐9, another MMP family member, presents as a promising target for suppressing tumor immune evasion in PAs." (PMID 39688352, 2024). "The tumor-promoting MDSCs can also prepare a microenvironment or a premetastatic niche (pMN), enhance angiogenesis by secreting matrix metalloprotease 9 (MMP9), and promote the tumor mesenchymal-epithelial transition (MET) to facilitate tumor growth." (PMID 38474377, 2024). "Tumor cells have the capacity to generate MMP-2 and MMP-9, which inhibit the expression of tight junction proteins like claudin-5 and ZO-1, consequently causing disruption to the BBB." (PMID 38243240, 2024). "MMP-10 can also upregulate the expression of MMP-7, MMP-9, and MMP-13, which are critical for tumor progression." (PMID 39247608, 2024). "Immune cells, including macrophages and neutrophils, can produce MMPs such as MMP-9, which further contributes to the degradation of ECM components and facilitates tumor progression." (PMID 39200315, 2024). "NFATC1 increased BLCA to promote tumor cell growth/colony formation and also promoted tumor migration and invasion by increasing expression of MMP2 and MMP9." (PMID 38910160, 2024). "N2 neutrophils exert their pro-tumor effects through the release of matrix metalloproteinase 9 (MMP9), which promotes angiogenesis and tumor cell migration." (PMID 39769334, 2024). "Aparna and colleagues investigated the expression of MMP-2 and MMP-9 in HNSCC (tongue cancer; stages I and II) and correlated their expression with local recurrence, distant dissemination of tumor cells, and survival outcomes." (PMID 38611032, 2024).
tumor (continued). "Mechanistically, BDS-hEA prominently facilitated autophagic apoptosis in tumor tissues and decreased the levels of ki67, CD31, VEGF, MMP-9, p-AKT, and p-mTOR while simultaneously enhancing the p-AMPK expression." (PMID 39091624, 2024). "One of the studies discovered that exosomal GP73 secreted by tumor cells can enter other acceptor tumor cells with low GP73 expression, activating GSK-3β phosphorylation and inducing upregulation of MMP-1 and MMP-9, promoting tumor metastasis." (PMID 39845976, 2024). "Baicalin suppresses tumor growth in MDA-MB-231 cells by decreasing the expression of MMP-2, MMP-9, uPAR, and uPA by disrupting the p38MAPK signaling pathway (Wang X.-F." (PMID 39257397, 2024). "Next, we employed CellChat to conduct pathway-based analyses of ligand-receptor (L-R) interactions between MICA+/MICA− tumor cells and MMP9+/MMP9− macrophages." (PMID 38254761, 2024). "TANs 2 also regulate tumor growth via the IL-6/STAT3 axis and proangiogenic as well as metastatic markers, such as VEGF and MMP9." (PMID 39335210, 2024). "This molecule can promote EMT to participate in tumor cell migration and invasion by upregulating MMP2, MMP9 and other factors and can directly activate VEGF and HIF-1α to promote tumor angiogenesis and other aspects to promote tumor metastasis." (PMID 38486162, 2024). "Subsequently, experiments validated that DNA damage not only induced MICA expression in tumor cells via IRF1, but also upregulated PROS1 levels in HCC cells, stimulating macrophages to secrete MMP9." (PMID 38254761, 2024). "At the same time, the downregulation of MMP-9 will also inhibit the expression of vascular endothelial growth factor (VEGF), inhibiting tumor angiogenesis." (PMID 38803433, 2024). "Neutrophils promote tumor progression by releasing angiogenic factors, including vascular endothelial growth factor (VEGF), matrix metalloproteinase 9 (MMP-9) and prokineticin-2 (PROK2)." (PMID 38303053, 2024). "As demonstrated in the current study, DC(I + II) NPs inhibited not only the expression of stemness genes but also the TERT gene and its downstream genes (MMP9 and VEGF2) in both tumor tissues." (PMID 39076585, 2024). "MDSCs also promote neo-angiogenesis within the primary tumor bed by secreting factors such as MMP9, TGF-β, bFGF, and VEGF, enhancing the permeability of aberrant neo vessels and facilitating tumor cell extravasation, a crucial step in metastatic dissemination." (PMID 39513886, 2024). "Mast cells are typically located at the edge of tumors and stimulate angiogenesis, extracellular matrix breakdown, and tumor growth by releasing mediators such as VEGF and MMP9." (PMID 38408075, 2024). "Western blotting revealed lowered expression levels of PCNA, MMP2, MMP9, and VEGF, providing additional evidence for the anti-tumor efficacy of ZSTK474." (PMID 39466763, 2024). "Analysis from the acquired immunofluorescence pictures revealed that PTGS2, MMP9, MMP2, and CXCR 4 were mostly located around the nucleus in tumor tissues, and PPARG was mostly located inside the nucleus in tumor tissues." (PMID 38457601, 2024). "MMPs, including MT1-MMP, MMP2, and MMP9, are also involved in the CD44-promoted formation of new vasculature and tumour invasion, which can be enhanced by an activation of TGF-β with proteolytically activated MMP-9." (PMID 38791985, 2024). "The percentage of cells with strong positive staining was significantly higher for tumor tissue when treated with PYCR1, PEPD, and MMP-9 antibodies (p < 0.0001) and lower when treated with POX/PRODH (p < 0.0001)." (PMID 38275897, 2024).
tumor (continued). "Tumor cells and CAFs jointly secrete lysyl hydroxylase(LH) in conjunction with matrix metalloproteinase-9(MMP-9), which activates the TGF-β signaling pathway and promotes collagen cross-linking within the stromal matrix, subsequently enhancing tumor stiffness." (PMID 39680287, 2024). "Another mechanism by which ALA inhibits tumor metastasis is by reducing vascular endothelial growth factor (VEGF), MMP-2 and MMP-9 protein expression." (PMID 38541002, 2024). "Alternatively, their presence can promote tumor progression by secreting VEGF, aiding angiogenesis, and MMP9, degrading the ECM, thus facilitating metastasis." (PMID 38397465, 2024). "We found that cysteamine treatment at micromolar concentrations specifically targets MMP2, MMP9, and MMP14, leading to the inhibition of tumor invasion and migration in GBM cells overexpressing these genes." (PMID 38893149, 2024). "MMP-9 also accelerates the degradation of local ECM, leading to the release and activation of other tumour-promoting factors stored in the local ECM of NETs." (PMID 38912060, 2024). "The binding of CD11b to ICAM1 on tumor cells triggers activation of the MAPK pathway within tumor cells, leading to the upregulation of MMP9 expression." (PMID 38907234, 2024). "The exosomal miR-210 derived from tumor cells induces the reprogramming of NFs to CAFs through TET, further promotes tumor angiogenesis and progress by producing MMP9, FGF2 and VEGF." (PMID 38825680, 2024). "By liberating vascular endothelial growth factor (VEGF) from angiogenic islets, MMP-9 is known to initiate the angiogenic migration in cancer, whereas MMP-2 controls the bioavailability of dissolved VEGF-A and tumor vascular patterning." (PMID 38672151, 2024). "Garcinol inhibits matrix metalloproteinase-9 (MMP-9), an enzyme involved in tumor cell invasion, and vascular endothelial growth factor (VEGF), a key regulator of angiogenesis (the formation of new blood vessels)." (PMID 39066940, 2024). "This analysis prompted a focus on specific MMPs more distinctly expressed in CC2, such as MMP2, MMP9, MMP11, MMP14, and MMP25, suggesting their potential role in tumor invasion and their clinical relevance as potential therapeutic targets." (PMID 38893149, 2024). "This highlighted that MMP9 secretion subsequently facilitated the proteolysis of MICA, thereby promoting the evasion of the tumor from immune surveillance." (PMID 38254761, 2024). "For example, MMP-14 can induce collagen I, II, and III in the tumor extracellular matrix, and MMP-2 and MMP-9 can degrade collagen IV, thus mediating tumor cell invasion into the basement membrane and inducing tumor invasion and metastasis." (PMID 39408814, 2024). "Several studies have demonstrated a strong correlation between the expression of MMP-1, MMP-2, MMP-7, MMP-9, MMP-10, and MMP-12 enzymes, tumour size, cancer progression, lymphatic dissemination, and bloodstream distant metastasis (table in Section 5)." (PMID 39337393, 2024). "MMP9+ TAMs are another crucial subset in the TME, correlating to the epithalami–mesenchymal transition (EMT) of tumour cells." (PMID 38303024, 2024). "Matrix metalloproteinase 9 (MMP9) activity is decreased by PTX treatment, which is identified to play a crucial control over the tumor microenvironment and the development of cancer." (PMID 38291541, 2024). "In this study, expression levels of MMP9 and MICA were significantly elevated in macrophages and tumor cells, respectively." (PMID 38254761, 2024). "MMP-2 and MMP-9 are among the most widely studied biomarkers of the MMPs family, which can degrade the ECM and basement membrane of tumor cells, thereby facilitating cancer cell migration and invasion." (PMID 39769029, 2024). "Knockdown of AAK1 substantially suppressed tumor growth, tumor weight, as well as the expression of AKK1, Notch3, GLS, MMP-2, MMP-9, and Ki-67 percentage." (PMID 38169546, 2024).
tumor (continued). "MDSCs, TAMs, and neutrophils produce various proteases, including matrix metalloproteinase 9 (MMP-9), fostering matrix digestion and remodeling to facilitate tumor cell migration and extravasation into blood vessels." (PMID 38732051, 2024). "Patient 2, who was diagnosed with recurrent ACP after primary tumour resection, showed the highest expression levels of CTSK and MMP-9." (PMID 38594611, 2024). "This combination not only reduces cell proliferation, but also hinders metastasis by downregulating key proteins, such as vimentin and MMP9, while affecting signaling pathways, such as Akt and STAT3, to enhance tumor inhibition." (PMID 39741633, 2024). "This transformation, coupled with the MMP-9 x LCN2 complex, enables the cells to remodel their surrounding ECM and enhance tumor cell invasion." (PMID 39188682, 2024). "They release molecules such as CCL2/3/4/17, Neutrophil Elastase, MMP9, and elevated arginase, contributing to immunosuppression and TME remodeling that fosters tumor progression." (PMID 38361931, 2024). "For example, MMP13 (Matrix Metalloproteinase 13) secreted by fibroblasts promotes tumor angiogenesis, while MMP2 (Matrix Metalloproteinase 2) and MMP9 (Matrix Metalloproteinase 9) degrade ECM (Extracellular Matrix) components to promote metastasis." (PMID 38782818, 2024). "In tumor tissues, overexpression of miR-22 also diminished the expression of NLRP3, MMP-2, and MMP-9 compared with the model group." (PMID 39858430, 2024). "MT1-MMP activates MMP-9 bound to CD44, which activates TGF-β and releases VEGF trapped in the ECM accelerating tumor-related angiogenesis." (PMID 39199626, 2024). "Matrix metallopeptidase 9 (MMP9), a member of the MMP family, is a major regulator of extracellular matrix turnover and thereby facilitates tumor metastasis." (PMID 39085398, 2024). "The increased MMP9 activity resulted in the proteolytic shedding of MICA, leading to the release of soluble MICA (sMICA) and the subsequent facilitation of tumor immune escape." (PMID 38254761, 2024). "MMP-2, MMP-9, and MMP-14 can be upregulated in some types of tumor cells through a hypoxia-inducible factor (HIF)-dependent mechanism." (PMID 39408814, 2024). "MMP-9 expression is elevated in TME and is directly correlated with clinical outcome of tumor invasion and metastasis." (PMID 39351229, 2024). "In S180 tumor-bearing mice, IAPS-2 promotes the secretion of several M1 markers and reduces the concentration of MMP-9 and VEGF in the tumor, restoring the immunosurveillance with an anti-angiogenetic effect." (PMID 38397187, 2024). "The results of Western Blot showed that the expression levels of the neovascularization markers, Flk-1, MMP9, and VEGF, in the tumor tissues of the PLA-drug group were significantly lower than those of the other three groups." (PMID 38526656, 2024). "Firstly, MDSCs play a role in promoting tumor angiogenesis through the secretion of factors like vascular endothelial growth factor (VEGF) and matrix metalloproteinase 9 (MMP9)." (PMID 38399305, 2024). "Targeting FLNB in fibroblasts was shown to increase matrix metallopeptidase-9 (MMP9) and VEGF secretion which led to induction in tumor growth." (PMID 39197170, 2024). "C-Myc, MMP9, CyclinD1, and BCL-2 were tumor-related genes that have been identified to be regulated by NFκB signaling." (PMID 38581570, 2024). "Increased MMP9 expression was found in LK0902/0861CAF spheroids and LK0923/0836CAF spheroids compared to spheroids with tumor-matched CAFs." (PMID 38822309, 2024). "Meanwhile, in vivo experiments demonstrated that HMPOC@M+laser treatment strongly attenuated liver and lung metastasis and inhibited tumor growth by downregulating VEGF and MMP9 proteins." (PMID 38731434, 2024). "For instance, sulforaphane demonstrates anti-tumor properties by regulating several signaling pathways, such as Nrf2/Keap1, AKT1/HK2, and NF-κB/MMP-9." (PMID 38612546, 2024).
tumor (continued). "The tumor-bearing animals treated with the polyphenol demonstrated significantly lower MMP-2 and MMP-9 serum concentrations compared to the untreated group." (PMID 39335164, 2024). "MMP-10 can also upregulate the expression of MMP-7, MMP-9, and MMP-13, which are critical for tumour progression." (PMID 38911387, 2024). "Ultimately, the evidence supports MMP9 as a critical mediator in CRC, aiding tumor invasion and metastasis, and its increased activity due to chemotherapy is suggested as a potential risk for developing CIPN." (PMID 39664453, 2024). "MST1 then recruits macrophages into tumor tissue and macrophage polarization to M2 type, which secrete MMP2 and MMP9 to promote HCC cell dissemination." (PMID 39695147, 2024). "Tumors enriched in MMP-9-delivering TAN are characterized by enlarged vessels (11–20 μm in diameter), which are partially covered by pericytes, suggesting a possible way for tumor dissemination." (PMID 39086395, 2024). "Regarding MMPs, a slight decrease was observed in the expression of MMP-9, and the level of TIMP-1 was increased; however, lower levels of MMP-2 and TIMP-2 were detected in tumorous tissues compared to adjacent healthy tissue samples." (PMID 39062015, 2024). "Our recently published data show that tumor-matched CAFs increased the mRNA expression of MMP1, MMP9 and FMOD in tumor cells when cocultured compared to tumor cells cultured alone in spheroids." (PMID 38822309, 2024). "MMP-9, upregulated in angiogenic islets and tumors, enhances the bioavailability of VEGF to its receptors, crucial for angiogenic switching and subsequent tumor growth." (PMID 39493763, 2024). "NFATC1 increase BLCA to promote tumor cell growth/colony formation, and can also promote tumor migration and invasion by providing the expression of MMP2 and MMP9." (PMID 38910160, 2024). "Researchers have also found that altering MMP-9 and MMP-2 expression leads to increased activity and tumor aggressiveness." (PMID 39769318, 2024). "Tumor cells, along with peritumoral macrophages and stromal cells, contribute to the dynamic changes in the ECM by expressing MMP9." (PMID 39664453, 2024). "Consistently, the results of Western blotting assay revealed that TIM3-mimic group had notably higher protein expressions of tumor invasion and metastasis-related molecules, matrix metalloproteinase-2 (MMP-2) and MMP-9 in TC cells than TIM3-NC group." (PMID 38568917, 2024). "MMP-9 released by neutrophils promotes the activation of VEGF and subsequent angiogenesis and tumor progression." (PMID 38580870, 2024). "AXL tyrosine kinase promotes tumor progression through AKT/GSK-3β/β-catenin signaling, β-catenin nuclear-translocation-induced SNAIL transcription, and MMP-2 and MMP-9 activation." (PMID 37046676, 2023). "Surprisingly, we found a higher proportion of macrophage C4 in brain metastatic tissues, and this macrophage subpopulation was highly expressed in genes that promote tumor invasion and metastasis, such as CSTB, MMP9, CCL5, and MIF." (PMID 37715019, 2023). "In another study, baicalein suppressed MMP-2 and MMP-9 and inhibited DLD1 tumor growth and metastatic effects by inhibiting phosphorylation of ERK." (PMID 36765950, 2023). "In tumor angiogenesis, MMP-2 and MMP-9 have been shown to be critical during the “angiogenic switch”." (PMID 36759828, 2023). "A recent body of evidence reports that KISS-1 is considered to be a potential tumor suppressor in a number of different tumors and is involved in cell proliferation, migration and invasion by targeting the MAPK/ERK and P50/MMP-9 pathways." (PMID 37024487, 2023). "Taken together, macrophage-derived MMP-9 and MMP-2 were closely related to the rupture of the FC of HCC and subsequently led to the migration and invasion of the tumor cells through the ruptured area of FC to the para cancer." (PMID 36918768, 2023).